RNU6-1233P (RNA, U6 small nuclear 1233, pseudogene)
Gene: Small nuclear RNA gene on chromosome 3 (175,397,247 to 175,397,348, reverse strand). Ensembl gene ENSG00000199792.
Homologues: Orthologues: chimpanzee U6 (100% identical), macaque U6 (90% identical), dog U6 (78% identical), rabbit U6 (75% identical), mouse Gm22965 (71% identical). Paralogues in human: RNU6-1047P (86% identical), RNU6-1075P (86% identical), RNU6-393P (86% identical), RNU6-797P (86% identical), RNU6-1123P (85% identical), RNU6-1152P (85% identical), RNU6-1301P (85% identical), RNU6-16P (85% identical), RNU6-41P (85% identical), RNU6-44P (85% identical), RNU6-1083P (84% identical), RNU6-1159P (84% identical), and 1289 more.